DDR1 (discoidin domain receptor tyrosine kinase 1)
Diseases named in the same sentence as DDR1 in open-access papers (continued):
Sharing a sentence is not in itself a finding about the gene and the disease.
fibrosarcoma (2 papers, 2017 to 2021). A malignant mesenchymal fibroblastic neoplasm affecting the soft tissue and bone. "Thus, DDR1 appears to inhibit the ability of fibrosarcoma cells to colonise lungs in the HT1080 xenograft model." (PMID 34957097, 2021). "Although human fibroblasts express DDR2 but not DDR1, HT1080 human fibrosarcoma cells express both DDR1 and DDR2." (PMID 28270508, 2017).
invasive ductal breast carcinoma (2 papers, 2016 to 2020). The most common type of invasive breast carcinoma, accounting for approximately 70% of breast carcinomas. "Interestingly, the expression of DDR1 helps to clinically distinguish invasive ductal breast carcinomas, which are often cohesive and epithelial, from invasive lobular breast carcinoma which often generate mesenchymal cells that move through the stromal matrix in a “single file” arrangement." (PMID 26796961, 2016).
liver fibrosis (2 papers, 2022 to 2023). "Briefly, the progression of liver fibrosis can be promoted when DDR1 is overexpressed in hepatocytes, and invasion, migration and liver metastasis can be stimulated when DDR1 is overexpressed in tumour cells." (PMID 37007062, 2023).
Osteopenia (2 papers, 2020 to 2022). Osteopenia is a term to define bone density that is not normal but also not as low as osteoporosis. "The specific deletion of exon 8 of Runx2 in osteoblasts decreased bone formation and caused osteopenia in mice, and DDR1 deletion reduced Runx2 activity and decreased vascular calcification." (PMID 33003599, 2020).
psoriasis (2 papers, 2024 to 2025). An autoimmune condition characterized by red, well-delineated plaques with silvery scales that are usually on the extensor surfaces and scalp. "Meanwhile, LTA, TDRKH, and DDR1 were expressed exclusively in T cells from psoriasis biopsy samples, while HLA-E and ICAM3 exhibited psoriasis-specific- expression." (PMID 40564099, 2025). "Of the 12 altered protein, 5 protein-disease causalities were supported by MR, i.e., LTA-celiac disease (PIVW = 1.29 × 10−3), IL18BP-Crohn’s disease (PIVW = 4.04 × 10−2), DDR1-Graves’ disease (PIVW = 3.37 × 10−3), CDSN-psoriasis (PIVW = 4.02 × 10−7), and BTN3A2-SD (PIVW = 3.93×10−5)." (PMID 39009607, 2024).
testicular germ cell tumor (2 papers, 2023 to 2025). A germ cell tumor arising from the testis. "Our data indicated that DDR1 was positively correlated with drug metabolism: cytochrome P450 and metabolism of xenobiotics by cytochrome P450 pathway in HNSC and testicular germ cell tumors (TGCT), while negatively correlated in KIRP." (PMID 37031216, 2023).
thyroid cancer (2 papers, 2021 to 2023). "Moreover, in thyroid cancer cells, DDR1 silencing promoted differentiation." (PMID 34206590, 2021).
acne rosacea (1 paper, 2025). "However, the risk allele substantially enhances TFAP2A DNA binding, consistent with a model in which the rs1264326 daSNV enhances TFAP2A promoter binding to alter expression of DDR1 and PSORS1C1 pro-inflammatory genes and drive risk for acne rosacea." (PMID 40998781, 2025).
acute lung injury (1 paper, 2020). A condition of lung damage that is characterized by bilateral pulmonary infiltrates (pulmonary edema) rich in neutrophils, and in the absence of clinical heart failure. "Tetrahydroisoquinoline-7-carboxamide based DDR1 inhibitor 7ae developed to treat acute lung injury (ALI) bind tightly to DDR1, reducing its kinase activity." (PMID 33262947, 2020).
amyloid (1 paper, 2023). "We previously demonstrated that DDR1 inhibition with nilotinib lowers CSF Aβ levels and reduces CNS amyloid burden by PET in the same cohort of AD patients." (PMID 37194065, 2023).
autism (1 paper, 2022). Persistent deficits in social interaction and communication and interaction as well as a markedly restricted repertoire of activity and interest as well as repetitive patterns of behavior. "Overall, the literature on the ITGB3BP, DDR1, and MMP8 genes indicates that the observation regarding the integration of transcriptome and exome genotyping in autism is a notable addition for the understanding of the genetics of autism." (PMID 35215271, 2022).
autism spectrum disorder (1 paper, 2022). A spectrum of developmental disorders that includes autism, and Asperger syndrome. "The integration of significantly up- and downregulated genes and genes of significant SNPs identified regulatory variants (rs6657480, rs3130780, and rs1940475) associated with the up- (ITGB3BP) and downregulation (DDR1 and MMP8) of genes in autism spectrum disorder in people of Arab ancestries." (PMID 35215271, 2022). "Regulatory variations (rs6657480, rs3130780, and rs1940475) identified the up- (ITGB3BP) and downregulation (DDR1 and MMP8) of genes in autism spectrum disorder in patients of Arab ancestry discovered through the integration of up- and downregulated genes and genes of significant genotypes." (PMID 35215271, 2022).
autoimmune disease (1 paper, 2016). A disorder resulting from loss of function or tissue destruction of an organ or multiple organs, arising from humoral or cellular immune responses of the individual to their own tissue constituents. "Accordingly, DDR1 may play an important biological role by facilitating the migration and the positioning of effector T cells in collagen-rich tissues during adaptive immune response and autoimmune diseases." (PMID 27391444, 2016).
Autoimmunity (1 paper, 2022). The occurrence of an immune reaction against the organism's own cells or tissues. "The lower expression of epithelial adhesion molecules, such as DDR1 and E-cadherin, facilitates damage to melanocytes and exposure of antigens that favor autoimmunity." (PMID 35643735, 2022).
Azoospermia (1 paper, 2017). Absence of any measurable level of sperm,whereby spermatozoa cannot be observed even after centrifugation of the semen pellet. "In fact, integrative DNA methylation and gene expression analysis has been successfully used to identify a novel dysregulated biomarker discoidin domain receptor 1 (DDR1) in non-obstructive azoospermia (NOA) patients." (PMID 28553232, 2017).
bipolar disorder (1 paper, 2024). A disorder of the brain that causes unusual shifts in mood, energy, activity levels and the ability to carry out day-to-day tasks. "In addition, genome-wide association studies found associations between DDR1 SNPs and SCZ and bipolar disorder (BD)." (PMID 38395959, 2024).
calcification (1 paper, 2026). Process by which organic tissue becomes hardened by the physiologic deposit of calcium salts. "Only a limited number of studies have explored DDR1‐induced arterial calcification using aortic models, and knowledge regarding DDR1‐mediated medial calcification in femoral arteries remained elusive so far." (PMID 41399911, 2026). "Together, these results demonstrate a crucial role for DDR1 in promoting calcification of femoral, but not carotid, VSMCs, highlighting a vascular site‐specific DDR1 involvement in vascular calcification." (PMID 41399911, 2026).
celiac disease (1 paper, 2024). An autoimmune genetic disorder with an unknown pattern of inheritance that primarily affects the digestive tract. "For example, significantly increased expression of LTA (P = 2.20 × 10−16) in celiac disease, IL18BP (P = 3.28 × 10−10) in Crohn’s disease, and DDR1 (P = 2.20 × 10−16) in Graves’ disease were observed." (PMID 39009607, 2024).
chronic hepatitis (1 paper, 2023). An active inflammatory process affecting the liver for more than six months. "Moreover, the serum DDR1 level is significantly higher in HCC patients than in chronic hepatitis patients and healthy individuals." (PMID 37007062, 2023).
chronic obstructive pulmonary disease (1 paper, 2020). A chronic and progressive lung disorder characterized by the loss of elasticity of the bronchial tree and the air sacs, destruction of the air sacs wall, thickening of the bronchial wall, and mucous accumulation in the bronchial tree. "Similarly, I have found that discoidin domain receptor 1 (DDR1/PTK3) is strongly linked to chronic obstructive pulmonary disease (COPD), a type of obstructive pulmonary disease typified by having long-term respiratory problems and a weak airflow." (PMID 32512817, 2020).
chronic pancreatitis (1 paper, 2021). A chronic inflammatory process causing damage and fibrosis of the pancreatic parenchyma. "Nevertheless, the use of highly selective agents against DDR1 and 2 receptors along with gene silence and knockout models may provide better molecular understanding on these novel targets to explore for chronic pancreatitis therapy." (PMID 34145346, 2021).
Cognitive impairment (1 paper, 2021). Abnormal cognition is characterized by deficits in thinking, reasoning, or remembering. "Conversely, later in adulthood DDR1 is mainly expressed in astrocytes and microglia and could be involved in degenerative processes related to cognitive impairments also observed in chronic SCZ." (PMID 34323026, 2021).
colon adenocarcinoma (1 paper, 2022). "DDR1 mRNA expression has been determined by RT-qPCR on 65 colonic adenocarcinoma samples and 78 colonic mucosa samples." (PMID 35205677, 2022). "LCM was performed on 25 colon adenocarcinoma samples and RT-qPCR revealed that DDR1 mRNA expression was higher in the tumoral area than in the stroma." (PMID 35205677, 2022). "In this study, we investigated the expression of DDR1 using immunohistochemistry in colon adenocarcinoma and studied the link between DDR1 expression with clinicopathologic and molecular parameters, including overall and event-free survival." (PMID 35205677, 2022). "Taken altogether, our results show that DDR1 is highly expressed in most colon adenocarcinomas and appears as an indicator of worse event free survival." (PMID 35205677, 2022). "Immunohistochemical expression of DDR1 was evaluated on 292 colonic adenocarcinomas." (PMID 35205677, 2022). "Moreover, any significant association between DDR1 mRNA expression and OS or EFS has been found in our cohort of patients undergoing surgery for colonic adenocarcinoma." (PMID 35205677, 2022). "The invasion capacity of colon adenocarcinoma is supported by DDR1 expression." (PMID 35205677, 2022). "Thus, our results showed that DDR1 was highly expressed in most colon adenocarcinomas and appears as an indicator of worse event free survival." (PMID 35205677, 2022).
crescentic glomerulonephritis (1 paper, 2018). A histopathologic term for a pattern of diseases characterized by extensive crescent formation in the glomeruli; patients present clinically with rapid deterioration of renal function, and possible progression to end-stage renal failure within weeks or months. "The present study investigated the role and relevance of DDR1 in human crescentic glomerulonephritis (GN)." (PMID 29859097, 2018).
demyelinating disease (1 paper, 2023). A broad group of disorders that affect the myelin sheaths that cover the neurons. "Taken together, the current study described, for the first time, the role of Ddr1 in myelin development and repair in the CNS, providing a novel molecule target for the treatment of demyelinating diseases." (PMID 37373466, 2023).
ductal carcinomas (1 paper, 2007). "DDR1 encoding receptor tyrosine kinase was overexpressed in ductal carcinomas." (PMID 17389037, 2007). "Immunohistochemistry confirmed higher expression of DVL1 and EMP1 in lobular carcinomas and of DDR1 in ductal carcinomas (p < 0.0001)." (PMID 17389037, 2007). "Seven differentially expressed genes (KRT5, KRT6 and KRT17 between tumor and normal cells, CDH1, EMP1, DDR1 and DVL1 between lobular and ductal carcinomas) were verified by immunohistochemical detection of proteins on TMA slides comprising of cores from 119 cases." (PMID 17389037, 2007). "Epithelial membrane protein 1 (EMP1), discoidin domain receptor 1 (DDR1) and human homolog of the Drosophila dishevelled gene (DVL1) were found by pairwise comparison analysis to be differentially expressed between lobular and ductal carcinomas." (PMID 17389037, 2007).
endometrial cancer (1 paper, 2014). Primary or metastatic malignant neoplasm involving the endometrium (mucous membrane that lines the endometrial cavity). "Immunoblotting confirmed that TNK2 and DDR1 are endogenously expressed in endometrial cancer cells." (PMID 25427824, 2014). "Immunoblotting confirmed TNK2 and DDR1 expression in endometrial cancer cell lines." (PMID 25427824, 2014). "However, from an analysis of the TCGA endometrial cancer data, increased TNK2 and DDR1 copy number appears to reflect regional gains rather than focal amplification, thus making their potential biological relevance in endometrial cancer difficult to predict." (PMID 25427824, 2014).
endometrial tumors (1 paper, 2014). "We next used quantitative real-time PCR to determine whether TNK2 or DDR1 were affected by copy number alterations among the 112 endometrial tumors in this study." (PMID 25427824, 2014). "We therefore extended our analysis of TNK2 and DDR1 to sequence the remaining coding exons from the 40 tumors in the discovery screen and to sequence all coding exons of TNK2 and DDR1 from another 72 primary endometrial tumors consisting of 10 clear cell, 21 serous, and 41 endometrioid tumors." (PMID 25427824, 2014).
endometrioid tumor (1 paper, 2014). A benign, borderline, or malignant epithelial tumor of the female reproductive system characterized by the presence of glands and/or cysts lined by neoplastic cells that resemble endometrial cells. "Of the three endometrioid tumors that harbored somatic DDR1 or TNK2 mutations, two cases (T88 and T117) were grade 1 and one case (T131) was grade 3." (PMID 25427824, 2014). "DDR1 was somatically mutated in 4.4% (2 of 45) of serous tumors and in 2.4% (1 of 41) of endometrioid tumors." (PMID 25427824, 2014).
glomerular disease (1 paper, 2018). "We have in fact observed a clear DDR1 tubular upregulation in human crescentic GN as well as in mouse models of glomerular disease." (PMID 29859097, 2018).
inflammatory bowel disease (1 paper, 2025). A spectrum of small and large bowel inflammatory diseases of unknown etiology. "DDR1 belongs to the DDR family, a unique group of receptor tyrosine kinases (RTKs) that are thought to play an important role in inflammatory bowel disease." (PMID 39940867, 2025).
keloid (1 paper, 2025). An irregularly shaped, elevated mark on the skin caused by deposits of excessive amounts of collagen during wound healing. "Moreover, dysregulated DDR1 expression is associated with impaired wound healing, as keloid fibroblasts express higher levels of DDR1 than normal fibroblasts, potentially contributing to keloid formation by promoting excessive collagen deposition." (PMID 40362249, 2025).
kidney (1 paper, 2022). "Thus, we performed a model of severe ischemia/reperfusion-induced acute kidney injury that progressed to kidney fibrosis in WT and Ddr1-null mice." (PMID 34941574, 2022).
kidney injury (1 paper, 2022). Trauma to the kidney. "Overall, we identified BCR and STAT3 as key players in DDR1-mediated proinflammatory and profibrotic effects after kidney injury." (PMID 34941574, 2022). "Thus, DDR1 contributes to acute and chronic kidney injury by regulating BCR and STAT3 phosphorylation and in turn the production of MCP-1 and TGF-β." (PMID 34941574, 2022).
lentivirus infection (1 paper, 2024). Virus diseases caused by the Lentivirus genus. "Using the RT-PCR, we observed that lentivirus infection markedly changed the DDR1 mRNA level in the presence of DOX." (PMID 39567474, 2024).
liver diseases (1 paper, 2023). "A brief overview of the potential roles of DDR1 and DDR2 in premalignant and malignant liver diseases is presented." (PMID 37007062, 2023).
lung diseases (1 paper, 2014). "DDR1 expression in heart and lung diseases may play a crucial role in regulating myocardial contractility, vascular remodeling, as well as in tissue microenvironment." (PMID 25369402, 2014).
metastasis (1 paper, 2015). The spread or migration of cancer cells from one part of the body (where they first appeared) to another. "Multivariate analysis demonstrated that DDR1 expression, together with some traditional prognostic factors, such as age, N stage and liver metastasis, were independent risk factors in the prognosis of PDAC patients." (PMID 26297342, 2015).
mucinous colorectal adenocarcinoma (1 paper, 2023). "and proteins involved in ECM organization, including DDR1, LAMA5, and TTR, were upregulated in mucinous colorectal adenocarcinoma." (PMID 37158593, 2023).
nasopharyngeal carcinoma (1 paper, 2020). A carcinoma arising from the nasopharyngeal epithelium. "Promising approaches are for example the combinations of Src-inhibitor dasatinib with EGFR-inhibitor afatinib in TNBC or DDR1-inhibitor 7rh in nasopharyngeal carcinoma." (PMID 32668815, 2020).
nephritis (1 paper, 2022). Inflammation of renal tissue. "Ddr1-KO mice have reduced renal levels of TGF-β in the UUO and NTS nephritis injury models, but whether this reduction was due to attenuated injury or a direct role for DDR1 in promoting TGF-β secretion is unclear." (PMID 34941574, 2022).
Obesity (1 paper, 2020). Accumulation of substantial excess body fat. "Taken together, these findings reveal that Ddr1 deficiency correlates with reduced obesity." (PMID 32360427, 2020). "We demonstrate in vivo for the first time a role for DDR1 in the regulation of obesity, glucose tolerance, adipose tissue fibrosis and beiging." (PMID 32360427, 2020). "We have uncovered new roles for DDR1 in the regulation of obesity, energy expenditure, adipose tissue fibrosis, and glucose homeostasis in vivo, and identified DDR1 as an important regulator of mesenchymal stem cell differentiation in vitro." (PMID 32360427, 2020). "•DDR1 deletion results in decreased obesity, and increased energy expenditure and brown fat activity." (PMID 32360427, 2020). "Moreover, MRTF-A deficient mice exhibit reduced obesity, improved glucose tolerance, and increased beige fat and UCP-1 expression, a phenotype similar to our DDR1-deficient mice." (PMID 32360427, 2020). "•DDR1 expression was increased in adipose and correlated with obesity and fibrosis." (PMID 32360427, 2020). "The fact that DDR1 could regulate RUNX2, cell trans-differentiation and fibrosis in the vascular system led us to question whether DDR1 might also regulate adipose tissue differentiation and remodeling in obesity." (PMID 32360427, 2020).
ocular tumor (1 paper, 2021). "After the specificity of the anti-DDR1 antibody was verified, we measured the expression of DDR1 in the primary ocular tumor specimens from patients with UM by using immunohistochemistry (IHC) staining with anti-DDR1." (PMID 33976105, 2021).
oral diseases (1 paper, 2024). "As DDR1 has been verified to be significant in the development of dental and periodontal tissues and the process of oral diseases, in the present study, we focused on the mechanisms controlling DDR1-mediated MMP-1, MMP-2, and MMP-13 expression in hPDLCs to demonstrate the role of DDR1 in ERR." (PMID 39596178, 2024). "Therefore, DDR1 is expected to play a regulatory role in oral diseases related with MMPs." (PMID 39596178, 2024).
osteoporosis (1 paper, 2020). A condition of reduced bone mass, with decreased cortical thickness and a decrease in the number and size of the trabeculae of cancellous bone (but normal chemical composition), resulting in increased fracture incidence. "Our findings may be applied to patients with osteoporosis or fracture as a basis for developing Ddr1-targeted therapy." (PMID 33003599, 2020).
plexiform neurofibroma (1 paper, 2025). An elongated and multinodular neurofibroma, formed when the tumor involves either multiple trunks of a plexus or multiple fascicles of a large nerve, such as the sciatic. "DDR1 and DDR2 are two of the most significantly repressed genes in plexiform neurofibroma mice after treatment with the kinase inhibitor cabozantinib." (PMID 40025071, 2025).